CD4 (CD4 molecule)
Diseases named in the same sentence as CD4 in open-access papers (continued):
Sharing a sentence is not in itself a finding about the gene and the disease.
infection (continued). "CD4 T cells from subjects W278 and B195 were also resistant to infection by HIV-1 R5, even though these EUs had the wild-type CCR5 molecule." (PMID 17092330, 2006). "Our studies have suggested that up to 60% of LP CD4+ T lymphocytes are lost as early as 2–3 wk into the course of infection." (PMID 17147468, 2006). "Early observations suggested binding to CD4 and the V3 region of gp120, blocking subsequent interaction between CD4 and gp120 and preventing infection of T lymphocytes, macrophages and cervical explant tissue." (PMID 16882346, 2006). "In infected individuals, viral production is a dynamic process involving continuous rounds of infection of CD4+ T lymphocytes with rapid turnover of both free virus and virus-producing cells that have a half-life of 1–2 days." (PMID 16412247, 2006). "Our results thus demonstrate that DC-mediated HIV-1 transmission requires 'regular' infection through CD4 and a co-receptor." (PMID 16916447, 2006). "Whereas HIV-1 entry into activated CD4+ lymphocytes leads to a productive infection, the virus encounter several blocks prior to integration in resting CD4+ lymphocytes." (PMID 16412247, 2006). "While these blocks delay the production of progeny virus following the infection of CD4+ resting T cells, mitogenic stimuli are able to trigger viral replication and release of infectious virus." (PMID 16412247, 2006). "In these studies, by binding HIV-1 Env, CD4 blocked the release of new viral particles and/or prevented the infection of new cells via CD4." (PMID 16764724, 2006). "A latent HIV-1 reservoir in resting memory CD4+ T cells is a major obstacle to the clearance of infection by HAART." (PMID 17014716, 2006). "In these studies, CD4+ T cells contribute to infection control by supplementing their helper role with cytotoxicity." (PMID 16494717, 2006). "The latent reservoir of human immunodeficiency virus type 1 (HIV-1) in resting CD4+ T cells is a major obstacle to the clearance of infection by highly active antiretroviral therapy (HAART)." (PMID 17014716, 2006). "Combined, the data provide evidence that intestinal inflammation and continual infection, destruction, and turnover of CD4+ T cells occur in patients on ART, suggesting that the major battle against HIV occurs in sequestered mucosal tissue sites." (PMID 17147469, 2006). "Anionic polymeric candidate microbicides are thought to interfere with HIV-1-cell interactions involving cellular receptors either directly in productive infection (CD4 and CXCR4/CCR5) or in cell to cell transfer of virus (DC-SIGN etc.)." (PMID 17042959, 2006). "Of course, comparison of this setting with ADC in which CD4 cells are often decreased underscores a switch from low-level and seemingly benign autonomous infection to more active and 'malignant' macrophage infection with resultant toxic sequelae." (PMID 16266436, 2005). "Given the higher levels of CD4 T cell activation observed in the acutely infected RMs as compared to the SMs in this study, it is conceivable that increased numbers of activated CD4 T cells provided additional cellular targets for infection." (PMID 16201015, 2005). "Infection was associated with the up-regulation of surface HLA class-II molecules and CD26, while the expression of CD4, tissue-specific markers, adhesion molecules and growth factor receptors was downregulated by the virus." (PMID 15857508, 2005). "CD4 down-regulation starts two days after infection and just a few hours before the cells are committed to die." (PMID 16107223, 2005). "In contrast, other studies have shown that viral sequences in env are more homogenous early in infection and diversify with disease progression and decline in CD4+ T cell counts." (PMID 16274482, 2005). "In an asymptomatic patient, a large reservoir of uninfected cells is available for infection by a second virus, as only 1:2,500 to 1:100,000 CD4 cells are estimated to be infected by HIV." (PMID 16107223, 2005).
infection (continued). "Optimal flow cytometry for determination of T cell subset profile, offers the added advantage that CD4/CD8 ratio will determine the infection status of the infant while the % CD4 will provide information on decision-making for commencement of HAART." (PMID 15683549, 2005). "Transitory infection refers to infection sustained by short-lived CD4+ T cells trafficking into the CSF space from the blood." (PMID 16266436, 2005). "It should also be noted that the infection rate of LNCaP cells by HIV was similar to that of HeLa-CD4, suggesting that the infectivity of HIV-1 for some types of CD4(-) cells is high." (PMID 16368003, 2005). "It is conceivable that an ineffective HPV-specific CD4+ T-cell response early during infection will allow HPV to persist and the establishment of high-grade disease." (PMID 15986031, 2005). "Antisperm antibody production is induced in themale genital tract when a local infection or disruption in the genital tract physical barrier leads toan influx of CD4+ T cells." (PMID 18476083, 1996). "We have shown that pulmonary Coccidioides posadasii infection leads to the accumulation of programmed death-ligand 1 (PD-L1)+Ly6G+ MDSC-like neutrophils that suppress CD4+ T cell proliferation and exacerbate disease by reducing protective Th1 and Th17 responses." (PMID 42206847, 2026). "The proportions of CD4+ T cells were unaffected during the infection." (PMID 41484094, 2026). "ratti infection, IL-9-producing CD4+ T cells were proportionally increased." (PMID 41901710, 2026). "Phenotypic analysis revealed that CD4+ T cellsexpressed IL-10 during infection across groups, but only ST2–/– infected mice showed higher expression intensity, measured as themean fluorescence intensity (MFI) of TNF-α and IFN-γ,indicating a shift toward a proinflammatory phenotype." (PMID 41365681, 2026). "Likewise, a higher CD4+CD25+Foxp3+ T cell frequency was observed in animals from the Lb/HSP65 group only at 7 weeks post‐infection." (PMID 40745935, 2026). "Mechanistically, LEF1 expression was significantly downregulated in CD4+ T cells post infection." (PMID 42192546, 2026). "Importantly, the degree of infection resistance correlates with a decrease in CCR5+ CD4+ T-cells, supporting CCR5 editing as an effective strategy to confer resistance to HIV in human T-cells." (PMID 41424846, 2026). "In the CL model by L. braziliensis, we observed an anti‐inflammatory effect, potentially caused by the significant increase in CD4+LAP+ and CD4+CD25+Foxp3+ T cell frequencies in draining lymph nodes from 6 to 8 weeks post‐infection in mice from Lb/HSP65 compared to Lb and Lb/Ø groups." (PMID 40745935, 2026). "Furthermore, STAT1 deficiency markedly reduced proportions of IFN-γ-producing CD8+ T cells and interleukin-10-producing CD4+ T cells at day 7 post-infection." (PMID 41910261, 2026). "The elevated presence of SARS‐CoV‐2–specific CD4+ TRM cells following breakthrough infection indicates that natural infection boosts tissue‐localised memory, which may be less robust following systemic vaccination alone." (PMID 41527553, 2026). "HIV-1 transmigration and infection of CD4+ T cells were quantified." (PMID 42079659, 2026). "Furthermore, the infection of CD4+CCR5+ cells by pseudoviruses containing the HIV-1 envelope was inhibited by TNFR2 protein." (PMID 42088414, 2026). "Notably, CD4+ TRM and SARS‐CoV‐2–specific CD4+ T cells were significantly more abundant in the NP of subjects with BR infections compared to HV subjects, even over 1 year after infection." (PMID 41527553, 2026). "However, because of the significant disparity between the cell–cell fusion and fusion in reverse infection results for WT CD4, it was worthwhile to examine CD4 and CD4-GPI virion incorporation levels in greater detail." (PMID 40284914, 2025). "Additionally, the CD3+CD4+ T lymphocyte subset was consistently higher in WCCs, both prior to and after infection, whereas RWFCs displayed a higher quantity of CD3+CD8α+ T lymphocytes." (PMID 40941329, 2025).
infection (continued). "We next asked whether colonic Salmonella-specific CD4+ T cells were still present at 4 wk after infection." (PMID 40924026, 2025). "Noteworthy, this effect could be rescued very early after infection (4 dpi) by depletion of CD4+ T cells suggesting that this OMM12 microbiome-intrinsic effect is present early or even prior to LCMV infection." (PMID 40274773, 2025). "To study this issue, we used an ex vivo human CD4+ T cell infection model developed in our laboratory to identify HIV-1 integration sites that might influence cell proliferation or survival." (PMID 40236153, 2025). "CLEC12A deficiency also activates splenic CD4+ T cells and CD8+ cytotoxic T cells upon infection." (PMID 41214106, 2025). "However, CD4 cells isolated from the three LN at day 14 post-infection comprised similar frequencies of TFH cells, matching the homogenous proportions of B220+IgG1+ GC B cells." (PMID 40092986, 2025). "Further work is also needed to determine whether these T-bet+ Tregs are derived from preexisting gut CD4+ T cell populations or whether they are generated peripherally de novo in response to infection." (PMID 40924026, 2025). "IFN-γ–producing CD4+ T cells are necessary but insufficient for protection against infection." (PMID 40463021, 2025). "However, CD4+ cell depletion did not affect DCC numbers or proliferation at 9 dpi, consistent with the accumulation of CD4 cells late during infection." (PMID 40739350, 2025). "Our results indicate that at least parts of the CD8αα+hiCD4-TCR1- cells rising after infection may indeed be αβ T cells (CD4-) in Salmonella-infected TCR Cγ−/− chickens." (PMID 40438105, 2025). "PLWH with a CD4 count < 200 cells/μL (<15%) and/or detectable HIV viremia face an increased risk of potentially life-threatening opportunistic infection via Monkeypox (Mpox) infection." (PMID 40872885, 2025). "Infection with IAV has also been shown to trigger the formation in the lungs of inducible bronchus-associated lymphoid tissues (iBALTs), which are lymphoid organizations that include primarily CD4+ and B cells." (PMID 40739350, 2025). "Single-cell RNA-Seq (scRNA-Seq) revealed transcriptional heterogeneity in brain CD3+ infiltrates, with CD4+ cells most prominent that displayed Th1- and Th17-like characteristics, and adoptive transfer of either subset in Rag1–/– animals during early infection prevented S. aureus outgrowth." (PMID 39989461, 2025). "Furthermore, although SARS-CoV-2-specific CD8+ and CD4+ T cells are elevated following infection, total T cell counts decrease during infection with SARS-CoV-2, because T cells are directly infected by SARS-CoV-2, triggering apoptosis (Footnotes C, D)." (PMID 40333247, 2025). "The expansion of polyclonal stem-like memory CD4+ T cells in third infection could therefore support the selection of a broad repertoire of B cells; as such, we argue that the slow acquisition of antiparasite immunity is not a failure of T cell help." (PMID 40214640, 2025). "Diminished CD8+ T cell response relative to CD4+ T cells at 6 months post-infection." (PMID 41262872, 2025). "Infection of human primary CD4+ cells with this mutant construct and one containing wild-type Rev gene led to a comparable induction of the quiescence programme, indicating that Tat may contribute to the induction of the HIV-induced quiescence programme." (PMID 41006834, 2025). "This shift in T cell composition contributes to the progressive decline and possible inversion of the CD4+/CD8+ ratio in older adults, a recognized hallmark of immunosenescence, which has been associated with heightened susceptibility to infection and increased all-cause mortality." (PMID 40777005, 2025). "Furthermore, we determined that microglia, macrophages, and CD4 + T cells were the primary cells producing IFN-γ during the early stages of this infection." (PMID 40471948, 2025).
infection (continued). "Additionally, other studies have reported that infection with a virulent strain of BoAHV-1 (Iowa strain) results in a reduction in circulating CD4+ and CD8+ T cells." (PMID 41150385, 2025). "Interestingly, an increase in experienced CM CD4 T cells and CM CD4 T cells expressing CD127 or TIM-3, which were higher after transplantation and with ATG induction, was associated with increased risk of infection." (PMID 40475763, 2025). "Similarly, early-activated CD25hi CD4+ T cells (day 3 post-infection), which lack CXCR5 expression, almost exclusively develop into terminal Th1 effector cells, whereas CD25lo cells, which generally express CXCR5, give rise to Tfh and TCM cells." (PMID 40391228, 2025). "It was found that all viruses could be effectively cell-to-cell transferred to macrophages from CD4 + T cells, and the cell-to-cell infection mechanism for HIV-1 transmission includes brain myeloid cells engulfing or fusing with HIV-1-infected CD4 + T cells." (PMID 40386405, 2025). "That study showed a significant elevation of CD4+CD45RO+ at D7 after infection." (PMID 41012122, 2025). "However, as the infection progresses, apoptosis and the cytopathicity of the virus lead to massive depletion of CD4+ T cells, especially in the gastrointestinal tract." (PMID 40141240, 2025). "This depletion may be a consequence of CD4+ T cells apoptosis in the liver and spleen of L. chagasi-infected hamsters induced by Leishmania antigen stimulation in the early period of infection." (PMID 40929455, 2025). "We also show that CD4+ T cell precursors against these antigens were detectable in the blood of infection-naive participants and observed that patients who had recovered from each of these infections demonstrated a memory or recall CD4+ T cell response to the antigen." (PMID 41061037, 2025). "Additionally, memory CD4+ T cells provide accelerated help and promote significantly earlier class switching in primary B cells compared to naïve CD4+ T cells over the course of an infection." (PMID 39887249, 2025). "These impairments could hinder the ability of CD4+ T cells to recognize and engage infected macrophages at the site of infection, a crucial step in controlling Mtb38,40." (PMID 41510269, 2025). "First, we asked whether the prior infection altered the ability of the structural cells to present antigen to CD4 and CD8 T cells." (PMID 40750594, 2025). "This C-to-G substitution at the −1 position was observed in all independent infection replicates, whether with cap1G- or cap3G-only viruses, and in both MT-4 and primary CD4+ T cells." (PMID 40035516, 2025). "An open question is whether the CD4+ T cells that enter the brain during S. aureus craniotomy infection prevent bacterial outgrowth in an Ag-dependent or -independent manner." (PMID 39989461, 2025). "For T/F HIV-1 from PWID, captured by circulating DCs followed by trans-infection to T cells may diminish the dependency on higher CD4 affinity during primary infection." (PMID 40408432, 2025). "Control of LASV replication in mice appears to be MHC dependent, with MHC-I–deficient mice (lacking CD8+ T cell responses) developing prolonged LASV infection, whereas MHC-II–deficient mice (lacking CD4+ T cell responses) are able to clear the infection." (PMID 40996813, 2025). "Timecourse studies in primary human CD4+ T cells following infection with the HIV reporter virus indicated that the level of KLF2 was significantly upregulated at 24 hpi and showed further increase at 48 hpi, reaching levels comparable to those in resting memory cells." (PMID 41006834, 2025). "However, in individuals with previous infection, vaccination reactivates CD4+ T cells with a distinct cytokine profile, producing IFN-γ and IL-10, different from those detected in subjects without previous infection." (PMID 40170841, 2025). "Dysfunctional glucose metabolism in CD4+ T cells is a characteristic feature of HIV+ infection." (PMID 40422863, 2025).
infection (continued). "CD4+ T lymphocytes are essential for patients to fight infection." (PMID 39792837, 2025). "Higher frequencies of PD-1-expressing CD4+ T cells were found in children in Mali after infection with P. falciparum, and blockade of PD-L1 and the inhibitory receptor LAG-3 restored CD4+ T cell function in mice infected with P. yoelii but not in those infected with P. chabaudi." (PMID 39847577, 2025). "Furthermore, IL-12 produced early during infection skews naïve CD4+ T cells to Th1 cells to establish Th1 cell-dependent host defense to L. monocytogenes infection in the adaptive immunity." (PMID 40979681, 2025). "FoxP3+ cells accounted for less than 5% of the total CD4+ T cell population and exhibited negligible levels of granzyme B and perforin expression, indicating that Tregs are unlikely to mediate the expression of granzyme B and perforin during the infection." (PMID 40590226, 2025). "We demonstrate that, despite sequence variation of the protein across these related fungi, exposure to Eng2 vaccinated and protected inbred and humanized HLA-DR4 strains of mice against lethal experimental infections with these fungi by eliciting adaptive immunity mediated by CD4+ T cells." (PMID 41061037, 2025). "Future studies should evaluate whether cluster-specific detection of C. parvum IIc warrants intensified infection prevention and control measures, given its persistence at higher CD4+ levels and possible altered virulence or transmission dynamics." (PMID 41148643, 2025). "Thus, during infection, activated CD4 T-cells show signs of exhaustion, which are reduced upon resolution." (PMID 41011738, 2025). "Whether RSV increases viral pathogenicity by skewing the CD4+ T-cell immune response through infection of distinct monocyte subsets needs to be determined." (PMID 39656009, 2025). "During untreated infection, only a small proportion of newly infected CD4+ T cells enter latency." (PMID 40464563, 2025). "However, development faces substantial challenges, such as the complexity of the viral life cycle, which includes persistent infection of CD4+ T lymphocytes and cell-to-cell transmission, making it difficult to induce effective immunity." (PMID 40723356, 2025). "The presence of parasite peaks in the animals can trigger the activation and clonal expansion of CD4 + Th cells, which are responsible for the immediate production of proinflammatory and anti-inflammatory cytokines, necessary to combat infection at each peak of antigenically distinct trypanosomes." (PMID 40743218, 2025). "A strong inverse correlation was observed between CD4 + T-cell count and infection prevalence." (PMID 41372782, 2025). "Quiescent CD4+ T cells exhibit high infection levels in AHI." (PMID 40143294, 2025). "Virologically, 93.6% (500/534) of patients had a viral load below 50 copies/mL at their last follow-up, indicating good infection control; 77.5% (414/534) had a CD4+ lymphocyte count above 500/μL, further indicating immunological stabilization due to antiretroviral therapy." (PMID 41003137, 2025). "Yet, the composition of the colonic immune compartment remained durably changed upon infection since infected mice showed a significant increase in the proportion of macrophages (F4/80+, CD11b+, Ly6C/G-), conventional CD4+ T cells (Foxp3-) and both TCRαβ+ CD8+ and TCRγδ+ CD8+ T cells." (PMID 40300021, 2025). "This vaccine would elicit virus-neutralizing antibodies to prevent infection and would generate type 1 cellular immunity, including antigen-specific Th1 CD4+ T-cells and CD8+ T-cells that recognize conserved viral antigens, eliminate infected cells, and prevent reinfection." (PMID 39692514, 2025). "Cell-free infection of primary CD4 T cells was also affected by IFNα." (PMID 40294108, 2025). "Collectively, this suggests that CD4+ T cell recruitment and/or activation could be hampered by cues generated from infection milieu that evolve as bacteria transition from planktonic to biofilm growth, which remains to be determined." (PMID 39989461, 2025).